ENSG00000256206 (novel protein)
Gene: Protein-coding gene on chromosome 11 (14,493,783 to 14,520,344, reverse strand). Ensembl gene ENSG00000256206.
Genetic constraint (gnomAD): Missense variants: 120 observed, 169.31 expected, observed/expected ratio (o/e) 0.71, 90% interval 0.61 to 0.82. Synonymous variants: 55 observed, 61.73 expected, observed/expected ratio (o/e) 0.89, 90% interval 0.72 to 1.12.